EPO (erythropoietin)
Diseases named in the same sentence as EPO in open-access papers (continued):
Sharing a sentence is not in itself a finding about the gene and the disease.
abdominal aortic aneurysm (6 papers, 2020 to 2025). Enlargement and ballooning of the vessel that supplies arterial blood to the abdomen, pelvis and legs. "In a recent work, EPO/EPOR signaling was considered to be evidence as an essential mediator of angiotensin-II-induced abdominal aortic aneurysm in Apoe−/− mice." (PMID 40259928, 2025). "Long term high-dose erythropoietin (EPO) had been reported inducing the formation of abdominal aortic aneurysm (AAA) in mice." (PMID 40191193, 2025). "The aim of this study is to investigate the renoprotective effect of erythropoietin (EPO) on hypovolemic shock and ischemia/reperfusion (IR) injury on kidneys as end-organs in an experimentally-created ruptured abdominal aortic aneurysm (rAAA) model." (PMID 32405372, 2020). "Recently, a new model of abdominal aortic aneurysm (AAA) has been developed by using EPO injection." (PMID 40191193, 2025). "The authors found higher pro-inflammatory signature in the aorta of EPO-treated mice and suggested that endothelial cell activation might be involved in EPO-induced abdominal aortic aneurysm." (PMID 36329047, 2022).
age-related macular degeneration (6 papers, 2018 to 2025). Age-related loss of vision in the central portion of the retina (macula), secondary to retinal degeneration. "Erythropoietin (EPO) is recognized for neuroprotective and angiogenic effects and has been associated with aging and neovascular age-related macular degeneration (AMD)." (PMID 29391474, 2018). "This population-based retrospective cohort study investigated the effectiveness of erythropoietin (EPO) treatment in reducing the risk of age-related macular degeneration (AMD) in hemodialysis patients, using the National Health Insurance Research Data of Taiwan." (PMID 36077032, 2022). "Erythropoietin (EPO) has been proposed to reduce the progression of atrophic age-related macular degeneration (AMD) due to its potential role in neuroprotection." (PMID 35884958, 2022). "The findings demonstrate that stable expression of EPO-R76E effectively protects ARPE-19 cells from oxidative stress-induced cell death, a process significantly implicated in the pathogenesis of age-related macular degeneration (AMD)." (PMID 41294847, 2025). "Erythropoietin, a potent angiogenic factor induced by ischemia, appears at higher concentrations in the eyes of patients with diabetic macular edema compared to those with age-related macular degeneration (AMD) or non-diabetic individuals." (PMID 41302503, 2025).
Allergy (6 papers, 2012 to 2024). An allergy is an immune response or reaction to substances that are usually not harmful. "Furthermore, the EPO activity indirectly indicates the eosinophils infiltration to site if injury and commonly implicated in the allergic diseases." (PMID 34452623, 2021). "Staining ECP (rather than MBP or EPO) as a markers of intensity of eosinophilic inflammation of the airways in allergic diseases, allowed us to compare our results with other DE controlled exposure studies." (PMID 26758251, 2016). "Breast milk involves no risk of allergy, contains antibodies, epidermal growth factor (EGF), and erythropoietin, which may promote the growth and repair of skin cells." (PMID 31027386, 2019).
Arthritis (6 papers, 2011 to 2021). Inflammation of a joint. "It is proposed that the reduction in the Hb count during arthritis results from reduced erythropoietin levels, a decreased response of the bone marrow erythropoietin and premature destruction of red blood cells." (PMID 19770265, 2011).
breast tumor (6 papers, 2016 to 2021). "Numerous tumor cells express the EPO receptor (EPOR), posing a risk that EPO treatment would enhance tumor growth, but the mechanisms involved in breast tumor progression are poorly understood." (PMID 28418910, 2017). "Thus, our experiments in vitro and in vivo demonstrate that functional EPOR signaling is essential for the tumor-promoting effects of EPO and underline the importance of the EPO-EPOR axis in breast tumor progression." (PMID 28418910, 2017). "While functional EPOR signaling was essential for the breast tumor progression effect of EPO and emphasizes the importance of the EPO/EPOR axis, tumor growth was markedly reduced after the knockdown of EPOR." (PMID 34299300, 2021). "To investigate the role of EPOR in breast tumor progression we used a murine xenotransplantation model which simulated EPO therapy in cancer patients." (PMID 28418910, 2017). "If this observation in vitro holds in vivo it would imply that EPO-induced signaling interacts with Myc, which is frequently amplified and over-expressed in breast tumors." (PMID 28418910, 2017). "Preclinically, it was observed by injection of MMTV-Wnt-1 tumor cells into mammary fat pads of mice that inhibition of EPO-induced JAK2 activation by Fedratinib was synergistic with chemotherapy for breast tumor-initiating cells." (PMID 27494133, 2016). "Tumor growth in the MDA-MB-231-D3H2-shEPOR subgroup treated with doxycycline (shSCR+dox) was dramatically reduced and showed substantially lower expression of EPOR by in situ hybridization than the control subgroups, indicating that EPO-EPOR axis is active in breast tumor progression in this model." (PMID 28418910, 2017).
bronchopulmonary dysplasia (6 papers, 2014 to 2024). Bronchopulmonary dysplasia is a chronic respiratory disease that results from complications related to lung injury during the treatment of infant acute respiratory distress syndrome in low-birth-weight premature infants or from abnormal lung development in older infants. "In a recent study, EPO was suggested to promote lung repair at the 14th day in hyperoxia-induced bronchopulmonary dysplasia injury in neonatal mice." (PMID 39338226, 2024). "The aim of this study is to optimize the timing of erythropoietin gene modified mesenchymal stem cells (EPO‐MSCs) transplantation for bronchopulmonary dysplasia (BPD)." (PMID 30160360, 2018). "The aim of the present study is to investigate the protection effects of bone marrow mesenchymal stem cells (MSCs) in combination with EPO against hyperoxia-induced bronchopulmonary dysplasia (BPD) injury in neonatal mice." (PMID 27191651, 2016).
coagulation disorders (6 papers, 2017 to 2025). "No patients had a previous history of coagulation defects, VTE, chronic respiratory failure, nephrosis syndrome, or hormone therapy including erythropoietin." (PMID 28525975, 2017).
deficiencies (6 papers, 2008 to 2024). "There are several reasons leading to the higher RDW, including inflammation, oxidative stress, shortening of telomeres length, increased erythrocyte mechanical fragility, nutritional deficiencies, and deficiency or dysfunction of erythropoietin." (PMID 35658957, 2022). "This absolute EPO deficiency can be caused by a decrease in the EPO production and/or by errors in EPO-sensing." (PMID 33842503, 2021). "Some CKD patients may also present with a functional EPO deficiency or EPO resistance, where normal range EPO levels coexist with low hemoglobin (Hb) levels, indicating that the bone marrow response to endogenous and exogenous EPO is blunted in patients with CKD." (PMID 33842503, 2021).
folate deficiency (6 papers, 2017 to 2025). A nutritional condition produced by a deficiency of FOLIC ACID in the diet. "These are EPO treatment, vitamin B12 or folate deficiency, exposure to toxins like benzene and parvovirus infection." (PMID 28144286, 2017). "Folate supplementation has been associated with an enhanced effect of erythropoietin treatment in patients with folic acid deficiency; however, KIDIGO guidelines do not advocate the use of adjuvants (such as folic acid) except in instances of deficiency or inefficacy." (PMID 34886434, 2021).
Friedreich ataxia (6 papers, 2006 to 2020). An inherited condition that affects the nervous system and causes movement problems. "EPO treatment in patients with Friedreich ataxia suggested the possibility for EPO to increase capillary density in skeletal muscle." (PMID 33330462, 2020). "Clinical studies explored the safety and use of EPO and carbamylated EPO to increase frataxin levels for treatment of Friedreich’s Ataxia." (PMID 32038269, 2019). "Drugs such as varenicline, riluzole or erythropoietin in Friedreich’s ataxia were tested in the past." (PMID 23835634, 2013). "The use of EPO in the treatment of Friedreich ataxia is based on the increased in vitro frataxin expression in response to EPO." (PMID 17112370, 2006). "Interestingly, prolonged EPO administration increased muscle capillary density in Friedreich Ataxia patients and may therefore contribute to the improved motor function reported following EPO treatment." (PMID 23874302, 2013).
gastric cancer (6 papers, 2002 to 2024). A primary or metastatic malignant neoplasm involving the stomach. "Overall, these gene expression data further demonstrate the molecular fidelity of EPO-GEMMs to their human counterparts and identify pathways that may underlie both common and unique features of gastric cancer subtypes." (PMID 38177458, 2024). "In contrast, gastric cancer EPO-GEMMs were invasive and reproducibly metastasized to the liver, lungs, peritoneum and adrenal glands, as frequently observed in patients; however, the organotropism of metastases differed across genotypes." (PMID 38177458, 2024). "The portability, flexibility and speed of these gastric EPO-GEMMs creates new possibilities for exploring how gastric cancers evolve, spread and respond to therapy in the complex in vivo environment." (PMID 38177458, 2024). "Here we present a suite of fully somatic mouse models of gastric cancer, termed gastric cancer EPO-GEMMs, produced by delivery of genetic elements directly to the stomach using tissue electroporation." (PMID 38177458, 2024). "Taken together, our data establish gastric cancer EPO-GEMMs as fast and flexible models that recreate fundamental histological and molecular features of the CIN and GS subtypes of the human disease." (PMID 38177458, 2024). "The genetic elements in the gastric cancer EPO-GEMMs consisted of a transposase–transposon vector pair, used to express a defined oncogene, and a plasmid coexpressing Cas9 with a single-guide RNA (sgRNA), used to knock out a tumor-suppressor gene of interest." (PMID 38177458, 2024). "The genetic flexibility of the gastric cancer EPO-GEMMs eliminates the need for extensive strain intercrossing and enables rapid testing of any genetic combination by simply changing the sequence of electroporated constructs." (PMID 38177458, 2024). "Together, these data highlight the relevance of EPO-GEMMs as a robust platform to study metastatic gastric cancer and suggest a role for tumor genotype in metastatic organotropism." (PMID 38177458, 2024). "In conclusion, the results of this trial indicate that the described biweekly combination regimen of paclitaxel plus cisplatin±G-CSF and/or erythropoietin is an effective and tolerable regimen for disseminated gastric cancer." (PMID 12085176, 2002). "Furthermore, as shown here, gastric cancer EPO-GEMMs allow for straightforward molecular studies on tumor–host interactions, now appreciated as central to cancer biology and therapy response." (PMID 38177458, 2024). "The different metastatic profiles of gastric cancer subtypes in the EPO-GEMMs were unexpected." (PMID 38177458, 2024). "Taken together, these results show that MSI EPO-GEMMs largely recapitulate the genetic and immune-microenvironmental patterns of human MSI gastric cancers." (PMID 38177458, 2024). "Remarkably, 10–20% of gastric cancer EPO-GEMMs developed metastases to the ovaries, irrespective of genotype." (PMID 38177458, 2024). "Our data suggest that the combination of paclitaxel and cisplatin with or without G-CSF and/or erythropoietin has promising therapeutic activity in patients with advanced gastric cancer." (PMID 12085176, 2002). "Furthermore, that the erythropoietin producing cell may be the cell of origin of CCRCC (a cancer with many similarities to NETs), and that gastric carcinomas of diffuse type may originate from the ECL cell, whereas the endodermal stem cell most probably gives rise to cancers of intestinal type." (PMID 34948181, 2021). "First, a subset of EPO-GEMM animals develop metastatic spread to the ovaries, an enigmatic but clinically important facet of gastric cancer presentation that has not been previously modeled." (PMID 38177458, 2024).
glioblastoma (6 papers, 2022 to 2025). The most malignant astrocytic tumor (WHO grade IV). "Survival of the glioblastoma patients after surgery correlated inversely with cyst fluid level of erythropoietin (r = − 0.44; p = 0.045)." (PMID 35659255, 2022). "In the present study, the cyst fluid concentration of growth hormone correlated with tumor volume, and the concentration of erythropoietin correlated inversely with survival, possibly illustrating a role for these hormones in the growth of glioblastomas." (PMID 35659255, 2022). "Comparison between glioblastoma and meningioma patients showed insignificant difference in serum EPO between the two subgroups after RT (p3 = 0.586)." (PMID 36121548, 2022). "Statistical analysis showed a significant increase in serum EPO in glioblastoma subgroup either prior to or following RT in comparison to healthy volunteers (p1 < 0.001 and < 0.001, respectively)." (PMID 36121548, 2022). "In glioblastoma patients pre-RT, the mean ± SD of serum EPO was 241.9 ± 46.95 that was decreased to 156.7 ± 19.56 post-RT, while it was 108.1 ± 10.04 in healthy controls." (PMID 36121548, 2022). "Among multiple onco-promoters produced by glioblastoma cells, erythropoietin was found." (PMID 41449467, 2025). "CAR-T cell therapy for glioblastoma (GBM) targets several antigens, including interleukin-13 receptor α2 (IL13Rα2), human epidermal growth factor receptor 2 (HER2), epidermal growth factor variant III (EGFRvIII), and erythropoietin-producing hepatocellular carcinoma A2 (EphA2)." (PMID 40092990, 2025). "Available evidence suggests roles for growth hormone, erythropoietin, and triiodothyronine in glioblastoma growth, but further studies are needed to establish whether the growth-stimulating concentrations of these hormones are within ranges found in the glioblastoma microenvironment." (PMID 35659255, 2022).
head and neck squamous cell carcinoma (6 papers, 2011 to 2017). A squamous cell carcinoma that arises from any of the following anatomic sites: lip and oral cavity, nasal cavity, paranasal sinuses, pharynx, larynx, and salivary glands. "Meanwhile, Mohyeldin and Lai also attested EPO was a crucial clinical signatures for head and neck squamous cell carcinoma diagnosis." (PMID 23825635, 2013). "There are reports on the relation of EPO and EPOR expression in other cells, such as endothelial cells and head and neck squamous cell carcinoma." (PMID 26376749, 2015). "The Hb trajectory can also explain why increasing the Hb level by transfusion or erythropoietin stimulation did not result in improved outcome for patients with low initial hemoglobin levels in head and neck squamous cell carcinoma." (PMID 27906669, 2017).
hemochromatosis (6 papers, 2009 to 2022). A disorder of iron metabolism characterized by a triad of HEMOSIDEROSIS; LIVER CIRRHOSIS; and DIABETES MELLITUS. "In addition to erythropoietin administration, two additional models of low systemic hepcidin were examined—administration of a low-iron diet to rats and a mouse model of juvenile hemochromatosis." (PMID 35682577, 2022).
hepatitis C (6 papers, 2010 to 2019). "control of blood products from the presence of hepatitis C and decreased blood transfusions by dialysis patients (due to increased use of erythropoietin), Hepatitis C transmission in dialysis units are still frequently observed." (PMID 23483113, 2013).
Hypoxemia (6 papers, 2008 to 2025). An abnormally low level of blood oxygen. "Hypoxemia was greatest in EBHD in response to the dynamic apnoeas and this was associated with an increase in serum EPO in EBHD only." (PMID 31563983, 2019). "Hypoxemia can upregulate the transcription factor hypoxia inducible factor-1 and induce a number of hypoxia-inducible genes, including erythropoietin." (PMID 25007716, 2014). "Hypoxemia is feature of COPD, which can stimulate a significant increase in serum erythropoietin, thereby inducing the generation of enlarged erythrocytes, resulting in an increase in RDW." (PMID 40168268, 2025). "Hypoxemia stimulates peaks of EPO release, and this increases not only the production of erythrocytes but also their size." (PMID 37958419, 2023).
ischemia reperfusion injury (6 papers, 2016 to 2025). Adverse functional, metabolic, or structural changes in ischemic tissues resulting from the restoration of blood flow to the tissue (reperfusion), including swelling; hemorrhage; necrosis; and damage from free radicals. "EPO cardioprotective activity in animal models of ischemia-reperfusion injury in heart was associated with Akt activation." (PMID 38628440, 2024). "Moreover, the protective effect of EPO on kidney cells was increased by its association with melatonin in a rat model of ischemia-reperfusion injury." (PMID 27504455, 2016). "Cardiac ischemia-reperfusion injury in rats also showed that EPO protective activity on mitochondrial dysfunction depended on the timing of EPO administration." (PMID 38628440, 2024). "In another study using a rabbit model of ischemia-reperfusion injury, EPO’s activation of the Ras/Rac/MAPK pathway was necessary for its protective effects." (PMID 36978804, 2023). "EPO stimulated increase in endothelial eNOS activation and NO production were required for EPO cardioprotection in an acute mouse model of ischemia-reperfusion injury." (PMID 36895793, 2023). "Based on our findings, the combined treatment with erythropoietin and methylprednisolone resulted in a significant therapeutic effect on the treatment of ischemia-reperfusion injuries of the spinal cord." (PMID 33767939, 2021). "In the mouse kidney ischemia–reperfusion injury (IRI) model, although a rapid increase in EPO expression was observed in the short term (12 hours), over a longer time range (14 days), EPO expression decreased in the injured kidney." (PMID 41179707, 2025).
kidney injury (6 papers, 2017 to 2025). Trauma to the kidney. "In the present study, we demonstrated that EPO could diminish the rhabdomyolysis-associated kidney injuries by ameliorating the infiltration of macrophages and promoting M2 polarization within kidneys during RIAKI." (PMID 28383559, 2017). "The current investigation was set out to assess erythropoietin (EPO) potential therapeutic benefits against thioacetamide (TAA)-induced kidney injury in rats." (PMID 37697015, 2023). "Specifically, we found that FUNDC1-mediated mitophagy is essential for EPO production in REPs during stress-induced kidney injuries and that damaged mitochondria accumulate in Fundc1-/- REPs as a result of impaired mitophagy." (PMID 33942716, 2021). "Erythropoietin (EPO) regulates the growth and differentiation of the erythroid progenitor cells by binding to the EPO receptor and has been widely used to treat kidney injury." (PMID 34571974, 2021). "Therefore, to sense acute and chronic kidney injury, we generated a lentiviral construct enabling the expression of target genes (including flag tagged murine EPO and IRES–GFP) under the control of a human Kim1 gene promoter." (PMID 41179707, 2025).
liver dysfunction (6 papers, 2019 to 2024). "In conclusion, our results demonstrated that EPO administration can reduce cholestasis-induced liver dysfunction." (PMID 32341967, 2019).